CYLD (CYLD lysine 63 deubiquitinase)
Diseases named in the same sentence as CYLD in open-access papers (continued):
Sharing a sentence is not in itself a finding about the gene and the disease.
tumor (continued). "The downregulation of CYLD is controlled by the transcription factor Snail1, which leads to an increase in levels of Cyclin D1, and N-cadherin, promoting tumor proliferation and invasion." (PMID 36139432, 2022). "One tumor with the D618A CYLD mutation was classified as NF-κB highly active, but this tumor also harbored simultaneous shallow TRAF3 and CYLD deletions." (PMID 35634245, 2022). "Decreased CYLD expression is involved in diverse kinds of tumor, CYLD has been regarded as a tumor suppressor gene." (PMID 36202787, 2022). "Querying only TRAF3 or CYLD defects would be blind to these alternative NF-κB activating strategies leading to imperfect tumor classification." (PMID 35634245, 2022). "Western blot analysis revealed lower expression of MARCH9 and higher expression of CYLD in the xenograft tumor tissues from the shMARCH9#1 group than tissues from the siCtrl group." (PMID 36185211, 2022). "We first sought to find the effective anti-tumor drugs for CYLD-knockdown OSCC cells, among the chemotherapeutic agents currently approved for standard treatment for OSCC patients." (PMID 36376983, 2022). "It has been reported that CYLD is involved in the pathogenesis of tumor progression via regulating a variety of intracellular signaling pathways as a deubiquitinating enzyme." (PMID 36376983, 2022). "We identified SPATA2 and its interacting partner, CYLD, as tumor-intrinsic regulators of T cell chemokines, including CXCL10, via a novel mechanism." (PMID 36531014, 2022). "The effects of different CYLD splice variants and the ratio of these variants on STAT1 accrual and signaling in CRC tumor cells merit future investigation." (PMID 36531014, 2022). "We therefore surmised that SPATA2 and CYLD suppress the production of T-cell chemokines from tumor cells, in part by regulating STAT1 protein levels and restraining STAT1 signaling (but not NF-κB signaling) emanating from IFN-γ stimulation." (PMID 36531014, 2022). "In vivo lncRNA GAS5 overexpression inhibited GH3 cell tumor growth, while miR-27a-5p mimic or silenced CYLD attenuated the effect of lncRNA GAS5 on GH3 cell tumor growth." (PMID 35435104, 2022). "Previous studies have shown that K63-specific DUBs, A20, and CYLD present the anti-tumor effects by regulating NF-κB signaling." (PMID 35874839, 2022). "CYLD is a tumor suppressor deubiquitinating enzyme that functions as an inverse modulator of the NFκB signaling pathway and is implicated in the regulation of tumor cell apoptosis." (PMID 34099061, 2021). "We first determined the interaction between SOX2 and CCAT1 and that between miR-222-5p and CYLD and their effect on tumor growth in vivo was analyzed in HCC-xenograft bearing nude mice xenografts." (PMID 33952719, 2021). "The authors demonstrated that CYLD-knockout mice displayed increased tumor growth compared to wild-type mice." (PMID 33800394, 2021). "Tumor protein analysis by Western blot also showed that the effect of CYLD depletion on p18 was retained in these tumors." (PMID 33654169, 2021). "We have found that attenuation in keratinocytes of the activation of NF-κB emerges as a very likely mechanism through which CYLD exerts its function as a tumor suppressor of skin squamous cell tumors." (PMID 34201751, 2021). "Another deubiquitinase that is well-known as tumor suppressor is the cylindromatosis (CYLD) tumor suppressor protein, a UCH deubiquitinase that predominantly removes K63- and M1-linked chains from target proteins." (PMID 33800394, 2021). "We show that Cd induces the formation of protein aggregates that sequester and inactivate cylindromatosis (CYLD) and selective autophagy, two tumor suppressors that deubiquitinate and degrade K63-ubiquitinated proteins, respectively." (PMID 34065348, 2021). "For example, the tumor suppressor cylindromatosis (CYLD), which is expressed in tumor cells, inhibits the proliferation and spread of tumor cells." (PMID 33498168, 2021).
tumor (continued). "We show here that the tumour suppressor CYLD is essential for CME of EGFR and its lysosomal degradation is induced by EGF and CTX in HNSCC cells." (PMID 35008337, 2021). "As CYLD functions as a tumor suppressor, its downregulation leads to the degradation of IκB and activation of NF-κB, resulting in apoptotic resistance in tumor cells." (PMID 34769401, 2021). "Compared with mice implanted with control shRNA infected cells, the tumor volume and tumor weight were significantly increased in mice injected with CYLD knockdown HONE1 cells." (PMID 33654169, 2021). "Some DUBs, including UCHL1, BAP1 and CYLD, are described as displaying intrinsic oncogenic or tumor suppressor activities." (PMID 34315490, 2021). "To investigate the effect of CYLD on EBV-mediated tumor cell growth, we conducted cell proliferation assays with CCK8." (PMID 33654169, 2021). "As an initiating event, we then looked for a partner of SQSTM1, the K63 deubiquitinase CYLD, which is a tumor suppressor that constitutively regulates the NF-κB pathway by removing K63-linked ubiquitin chains from TRAF6." (PMID 34065348, 2021). "In contrast to other oncogenic DUBs of the USP family, CYLD is the DUB with the most typical tumor suppressor effects." (PMID 34179009, 2021). "We also found that EBV deregulates the CYLD-p18 axis, which contributes to viral DNA replication and tumor growth." (PMID 33654169, 2021). "Similar to the results in our previous reports, tumour cells in more than half of the cases (16/29) showed lower CYLD protein expression levels (score 0–1), with this expression being absent (score = 0) in 31% (9/29) of cases." (PMID 35008337, 2021). "Next, to evaluate the relevance between CYLD and p18 in NPC, IHC staining of p18 and CYLD was conducted in a NPC tumor tissue microarray." (PMID 33654169, 2021). "Cylindromatosis (CYLD) functions as a deubiquitinating enzyme and exerts a tumor-suppressive role in multiple malignancies." (PMID 34099061, 2021). "Downregulation of CYLD is correlated with tumor initiation, development, metastasis, and resistance to treatment.However, the expression and function of CYLD in NPC is still unclear." (PMID 33654169, 2021). "Genetically engineered CYLD mouse models have firmly established a tumor suppressor function for CYLD." (PMID 33982884, 2021). "As a recognized tumour suppressor gene, CYLD has been extensively studied in many cancers, and it has been found that CYLD is phosphorylated in various cancer cells through IKK induction." (PMID 34711178, 2021). "Proteins were extracted from the tumor tissue and Western blotting showed that the expression level of CYLD phosphorylation was significantly lower in BTKis group compared with in control group." (PMID 33827598, 2021). "In LUAD cells, GMDS‐AS1 acts as a ceRNA, which promotes the expression of CYLD by sponging miR‐96‐5p, thereby inhibiting the proliferation of tumor cells and promoting apoptosis." (PMID 31860169, 2020). "As NF-kB signaling is a well-known pathway for promoting tumor angiogenesis and results showed increased total VEGF and VEGFA expression after CYLD knockout, tumor microvessel formation was investigated by IHC staining of Cd34 in xenografts." (PMID 32708712, 2020). "CYLD is a tumor suppressor that was initially identified in familial tumors including cylindromatosis, familial trichoepithelioma and Brooke–Spiegler syndrome." (PMID 32024820, 2020). "Initial studies characterized CYLD as a key regulator of the NFκB pathway and because of the well-known role of NFκB in inducing prosurvival genes, its tumor suppressor function was largely thought to be via suppression of NFκB44." (PMID 32024820, 2020). "The data are consistent with CYLD acting as a tumor suppressor gene to inhibit cell migration in vitro and metastasis in vivo." (PMID 32708712, 2020).
tumor (continued). "miR-362-5p was described as a tumor inducer in breast cancer, chronic myelocytic, and hepatocellular carcinoma and its amplification, by releasing the promotion upon tumor-inhibiting genes such as CYLD and GADD45α, promotes tumorigenesis and metastasis." (PMID 31925702, 2020). "A20 and CYLD act on several components of the pathway, downregulating NF-κB signaling and thereby acting as tumor suppressors." (PMID 32549302, 2020). "Both, primary tumor and metastatic Tg(Grm1) Cyld−/− cells display significantly increased migration compared to the cell lines derived from Tg(Grm1) Cyld+/+mice, whereas cell attachment was not influenced by CYLD." (PMID 31591386, 2019). "Originally identified as a tumor suppressor gene, CYLD is now known to be involved in the regulation of cell proliferation and is mutated in multiple tumors of skin appendages, referred to as cylindromas." (PMID 31795161, 2019). "The cylindromatosis (CYLD) gene, a tumor suppressor, has been initially identified as a responsible mutated gene because its loss causes a benign human tumor called cylindromatosis." (PMID 31635163, 2019). "Cylindromatosis (CYLD), a deubiquitinating enzyme, acts as a tumor suppressor in several malignancies." (PMID 31635163, 2019). "It is reported that the STAT3 directly activates MIR21 and MIR181b-1, respectively, suppressing the targets phosphatase and tensin homolog (PTEN) and CYLD (CYLD lysine 63 deubiquitinase) tumor suppressors." (PMID 31075975, 2019). "Next to its tumor suppressor function CYLD is also a key regulator of immunity and inflammation, which is demonstrated in multiple CYLD genetic mouse models." (PMID 29755980, 2018). "CYLD restoration in a CYLD-deficient NPC cell line, C666-1, confirmed its tumor-suppressive role in EBV(+) NPC cell context." (PMID 29933636, 2018). "CYLD was initially reported as a tumor suppressor with deubiquitinating enzyme activity that is mutated in familial cylindromatosis." (PMID 30285829, 2018). "Defects of A20 and CYLD are found in several types of cancer, which leads to the hyperactivation of NF-кB and triggers uncontrolled growth and metastasis of tumor cells." (PMID 30348973, 2018). "Allelic losses in 16q that contains the putative tumour suppressor gene CYLD were also observed in 9 of 20 (45%) tumours." (PMID 29416628, 2018). "How do the NF-κB defects (e.g. CYLD, TRAF3 aberrations) and the immune system defects (including MHC loss) lead to tumor formation, or immune evasion (e.g., via dysregulation of innate and adaptive immune responses) ?" (PMID 29933636, 2018). "Most important, CYLD defective tumor primary cell culture models on 3-D tissue culture scaffolds showed sensitivity to low micromolar levels of pegcantratinib, supporting our rationale of in vivo targeting in patients with CCS." (PMID 29955768, 2018). "Cylindromatosis (CYLD) is a deubiquitinating enzyme that was originally identified as a tumor suppressor in familial cylindromatosis, but has since then also been implicated in other cancer types." (PMID 29755980, 2018). "We demonstrated that CYLD defective tumour primary cell culture models on three-dimensional tissue culture scaffolds were highly sensitive to nanomolar levels of TRK inhibition." (PMID 28270164, 2017). "Tropomyosin receptor kinase (TRK) was discovered as a candidate target following a search for targetable kinases in inherited CYLD defective tumours using an unbiased genetic approach." (PMID 28270164, 2017). "Regulation of these signaling pathways are important for the tumor suppressor function of CYLD in different types of human cancer." (PMID 26973854, 2016). "Several studies showed that the tumor suppressor CYLD inhibits NF-kB as well as the p38 MAPK pathway activation by deubiquitinating several upstream regulatory signaling molecules of these pathways, thus suppressing these signaling pathways." (PMID 31093340, 2016).
tumor (continued). "Cylindromatosis gene, CYLD is a tumor suppressor gene that was originally identified as a gene mutated in familial cylindromatosis and related diseases." (PMID 26973854, 2016). "The tumour suppressor CYLD is a deubiquitinase previously shown to inhibit NF-κB, MAP kinase and Wnt signalling." (PMID 27561390, 2016). "In fact, in addition to this CYLD tumor suppressor, several key tumor suppressors and oncogenes such as the VHL, PDGFR-α, and Shh/Patched 1 (Shh/Ptch1) were recently identified to regulate ciliogenesis." (PMID 31093340, 2016). "We assessed MYB protein expression in inherited CYLD‐defective tumours (n = 16) to determine the frequency of MYB‐positive tumours in this group." (PMID 26969893, 2016). "The combined function of CYLD in modulating the activity of these pathways provides a rational mechanism for its important tumour suppressor role in a variety of human malignancies." (PMID 27561390, 2016). "CYLD was initially identified as a tumor suppressor and has recently been identified as an important ciliary regulator, as both CKO mice and transgenic mice carrying truncations in the carboxyl-terminal deubiquitinase domain of CYLD exhibit ciliary defects." (PMID 27028867, 2016). "At the same time, the expression levels of miR-130b were negatively correlated with the protein levels of CYLD in these tumor tissues." (PMID 27391066, 2016). "Further, inhibition of TRK signaling in CYLD-mutant tumor models demonstrated the potential efficacies of TRK targeting." (PMID 31093340, 2016). "CYLD has been recognized as a tumor suppressor by impairing cell proliferation and inducing cell death." (PMID 27391066, 2016). "The downregulation of miR21 and miR181b-1 and subsequent activation of PTEN/Akt and CYLD/IκB signaling axis leading to decreased NF-κB activity required to maintain the tumor-inhibiting effect of Rig-G.." (PMID 27602766, 2016). "It has reported that CYLD was a tumor suppressor that regulated cell apoptosis and necroptosis by acting as a deubiquitinating enzyme." (PMID 27738385, 2016). "It is possible that the negative regulation of NF-κB mediated by CYLD contributes to its tumour suppression function given the increasingly recognized role for NF-κB in cancer advancement." (PMID 27597804, 2016). "CYLD has been suggested to be a tumor suppressor gene, as supported by evidences from the first genetic susceptibility study for the CYLD cutaneous syndrome." (PMID 31093340, 2016). "The tumor suppressor CYLD is a deubiquitinating enzyme, acts as a negative regulator of NF-kappa-B signaling, and plays a pro-inflammatory role in vascular smooth muscle cells." (PMID 26540294, 2015). "Subcellular localization of CYLD was assessed by immunohistochemistry in tumor tissues of 95 HCC patients undergoing liver resection or transplantation." (PMID 25329885, 2014). "The increased expression of JAG2 in CYLD defective tumours in particular supported our in vitro findings that CYLD-MIB2 regulation of Notch signalling influences expression levels of the ligand JAG2." (PMID 25565632, 2014). "Taken together with our data showing CYLD defective tumours are sensitive to γ-secretase inhibitors, an oncogenic dependency on Notch is likely in this model." (PMID 25565632, 2014). "We have previously shown that JAG2 is upregulated in CYLD defective tumour tissue, particularly in “Wnt active” tumours." (PMID 25565632, 2014).
tumor (continued). "Taken together, these data validate the microarray data at the protein level and highlight CYLD defective tumours as a model tumour type characterised by aberrant Notch signalling." (PMID 25565632, 2014). "Particularly notable findings included CYLD-overexpressing tumors having a smoother hypoxic margin consisting of round tumor cells even after treatment (Fig. 3Blower middle and right panels)." (PMID 25071012, 2014). "Cylindromatosis (CYLD) is a tumor suppressor that regulates signaling pathways by acting as a deubiquitinating enzyme." (PMID 25071012, 2014). "Taken together these data indicate an oncogenic dependency on Notch signalling and suggest potential novel therapeutic approaches for patients with CYLD defective tumours." (PMID 25565632, 2014). "A number of Notch target genes were consistently overexpressed in CYLD defective tumours, including LEF1, HEY1 and NOTCH1." (PMID 25565632, 2014). "Nuclear HES1 was seen to be increased in CYLD defective tumours, but the difference from control epidermis was smaller than for LEF1 and RUNX1 (p = 0.027)." (PMID 25565632, 2014). "This study aimed to assess subcellular CYLD expression in tumor tissues and its prognostic significance in HCC patients undergoing liver resection or liver transplantation." (PMID 25329885, 2014). "Strikingly, the IHS for nuclear CYLD expression inversely correlated with both tumor grading (Spearman correlation coefficient −0.423, P<0.001) and Ki67-positivity (Spearman correlation coefficient −0.272, P = 0.005)." (PMID 25329885, 2014). "We assessed the expression of 98 Notch related transcripts, including Notch target genes and Notch signalling pathway components, in a dataset of gene expression profiles of CYLD defective tumours." (PMID 25565632, 2014). "To validate these findings, we performed quantitative PCR on RNA isolated from a subset of CYLD defective tumours used in the microarray study." (PMID 25565632, 2014). "The tumor suppressor function of CYLD in skin is due to the reduced proliferation rate mainly through a delay in the G1 to S phase transition by reducing cyclin D1 expression levels in a NF-κB dependent signaling pathway." (PMID 21573132, 2011). "The tumor suppressor CYLD is a deubiquitinating enzyme that inhibits activation of the NF-κB, which has key roles in inflammation and apoptosis." (PMID 20414373, 2010). "The tumor suppressor CYLD is directly phosphorylated by IKKε at serine-418 to decrease its deubiquitinase activity, which is essential to the IKKε-induced transformation." (PMID 20863366, 2010). "The CYLD gene, which is responsible for this syndrome, has been localized to chromosome 16q12-q13, and probably represents a tumour suppressor gene." (PMID 19725978, 2009). "This may suggest that tumor cells can evade immune-mediated killing by suppressing CYLD activity and stabilizing pro-survival signaling within the TNFR1 complex." (PMID 41315176, 2025). "We hypothesize that mGluR1 stimulates NF-κB through downregulation of CYLD to promote tumor growth; however, this theory requires further investigation and validation." (PMID 38672652, 2024). "Abnormal expression of Cylindromatosis (CYLD) has an important role in tumor development." (PMID 38287022, 2024). "Moreover, we discovered that CYLD inhibited tumor cell proliferation and enhanced the sensitivity to cell ferroptosis in PCa in vitro and in vivo, respectively." (PMID 38246916, 2024). "Our study reveals a tumor suppressive function of CYLD in the pathogenesis of DLBCL and MCL." (PMID 36922488, 2023). "HPV+ HNSCC cells in culture with experimental depletion of TRAF3 or CYLD displayed increased expression of the subclass-defining genes, as well as robust radio-sensitization, thus recapitulating both the tumor transcriptional state and improved treatment response observed in patient data." (PMID 37523561, 2023). "CYLD is a tumor suppressor that contributes to the regulation of NF-κB." (PMID 37892185, 2023).